CLCNKB (chloride voltage-gated channel Kb)
Diseases named in the same sentence as CLCNKB in open-access papers (continued):
Sharing a sentence is not in itself a finding about the gene and the disease.
epilepsy (2 papers, 2025). A brain disorder characterized by episodes of abnormally increased neuronal discharge resulting in transient episodes of sensory or motor neurological dysfunction, or psychic dysfunction. "In this study, we generated iPSC lines from individuals diagnosed with epilepsy who carry a novel mutation in the CLCNKB gene." (PMID 40600194, 2025). "For instance, mutations in the CLCNKB gene have been identified in several hereditary epilepsy syndromes, especially those associated with recurrent forms of epilepsy." (PMID 40600194, 2025). "This suggests a potential role for these genes in the pathophysiology of epilepsy linked to CLCNKB mutations." (PMID 40600194, 2025). "In our study, CLCNKB was identified through genetic screening in an epilepsy-affected family, whereas LARGE1 emerged from subsequent sequencing data analysis." (PMID 40600194, 2025). "The successful establishment of CLCNKB-mutant patient-specific iPSC lines and their transcriptomic characterization provide a valuable tool for studying the molecular basis of epilepsy." (PMID 40600194, 2025). "Instead of focusing solely on previously reported epilepsy-related genes, we extended our analysis to include both known and novel genes that may interact with CLCNKB and contribute to disease pathogenesis." (PMID 40600194, 2025). "Since the CLCNKB mutation identified in this family has not been previously reported in relation to epilepsy, we aimed to explore the downstream transcriptional changes using transcriptome analysis." (PMID 40600194, 2025). "However, since CLCNKB has not been previously reported to be associated with epilepsy, we expanded our analysis to include RNA-seq-based transcriptomic profiling." (PMID 40600194, 2025). "Although the direct effects of CLCNKB and LARGE1 in epilepsy require further validation, their roles in ion channel function and the glycosylation modification offer new perspectives for research." (PMID 40600194, 2025). "Based on the patient’s clinical manifestations, previously reported disease - related genes, and our comprehensive RNA - seq data, we tentatively speculate that CLCNKB and SLC12A1 may functionally coordinate in the pathophysiological context of epilepsy." (PMID 40600194, 2025). "We focused particularly on the roles of the CLCNKB and LARGE1 genes, which are involved in regulating neuronal excitability and the glycosylation modifications, potentially implicating them in the pathogenesis of epilepsy." (PMID 40600194, 2025).
Hearing impairment (2 papers, 2023). A decreased magnitude of the sensory perception of sound. "In the literature review, among the spectrum of clinical phenotypes reported for variants of the CLCNKA and CLCNKB, those associated with hearing loss are primarily linked with Type III or Type IV BS." (PMID 38069401, 2023). "The distinct presentation of non-syndromic hearing loss in the case involving a single copy loss of CLCNKB along with biallelic loss-of-function alleles in CLCNKA might be understood through the differential roles that these genes have in the inner ear and kidney." (PMID 38069401, 2023). "The current case suggests that an additional copy gene defect in CLCNKB, in combination with biallelic loss-of-function alleles in CLCNKA, contributed to the development of the hearing loss phenotype." (PMID 38069401, 2023).
Pendred syndrome (2 papers, 2019 to 2020). Pendred syndrome (PDS) is a clinically variable genetic disorder characterized by bilateral sensorineural hearing loss and euthyroid goiter. "In pendrin knockout (KO) mice, the CCD proteome was accompanied by strong downregulation of other IC markers like CLCNKB, BSND (Barttin), and VAA (vH+-ATPase), a configuration that may contribute to the salt-losing phenotype of Pendred syndrome." (PMID 35330743, 2020).
renal carcinoma (2 papers, 2020 to 2022). A carcinoma arising from the epithelium of the renal parenchyma or the renal pelvis. "Hypermethylation in deletions of CLCNKB in renal carcinoma further indicated its tumor-suppressing role in cancer." (PMID 33553144, 2020). "CLCNKB was previously reported to be downregulated in renal carcinoma." (PMID 33553144, 2020).
age-related macular degeneration (1 paper, 2022). Age-related loss of vision in the central portion of the retina (macula), secondary to retinal degeneration. "However, HMCN1 is reported to be associated with age-related macular degeneration and therefore does not represent a strong candidate in comparison to the known pathogenic p.Arg76Ter variant in CLCNKB." (PMID 35668994, 2022).
atrial septal defect (1 paper, 2019). Interauricular communication is a congenital malformation characterized by a communication between the atrial chambers of the heart. "We reported a unique case of CBS associated with GH deficiency and atrial septal defect (ASD) with a novel compound heterozygous mutation in the CLCNKB gene." (PMID 31409296, 2019).
breast carcinoma (1 paper, 2022). "Expression of metastatic state ion channels GRIK5 (p-value: 0.51) and CLCNKB (p-value: 0.18) were also associated with survival in breast cancer patients." (PMID 35326596, 2022).
diabetic retinopathy (1 paper, 2018). "This region spans genes with plausible roles in the development of diabetic retinopathy, (e.g. PADI1, PADI2, PADI3, and PADI4, as well as genes known to be involved in kidney function (CLCNKA and CLCNKB)." (PMID 29444168, 2018).
glioma (1 paper, 2019). A benign or malignant brain and spinal cord tumor that arises from glial cells (astrocytes, oligodendrocytes, ependymal cells). "The following four probes cg19681793 (targeting THBS2), cg24215279 (targeting TPO), cg11235583 (targeting CLCNKB), and cg14158583 (targeting PVRL4) have also been confirmed to target effective genes with different methylation status in different IDH-dependent glioma subtypes." (PMID 31803734, 2019).
kidney failure (1 paper, 2024). An acute or chronic condition that is characterized by the inability of the kidneys to adequately filter the blood. "We identified a family with a mixed Bartter/Gitelman phenotype and early-onset kidney failure and by employing a candidate gene approach, identified what we believe is a novel homozygous mutation (CLCNKB c.499G>T [p.Gly167Cys]) in exon 6 of CLCNKB in the index patient." (PMID 39405114, 2024).
kidney stones (1 paper, 2021). "The second younger brother of the proband harbored the same simultaneous mutations in SLC12A3 and CLCNKB and exhibited similar clinical features except normomagnesemia and bilateral kidney stones." (PMID 33807568, 2021).
polycystic kidney disease (1 paper, 2014). A usually autosomal dominant and less frequently autosomal recessive genetic disorder characterized by the presence of numerous cysts in the kidneys leading to end-stage renal failure. "A modifier effect from genetic and/or environmental factors as it has been often reported in other cases of CLCNKB mutation Sep and other human diseases such as polycystic kidney disease." (PMID 24711981, 2014).
sensorineural deafness (1 paper, 2023). "Moreover, the presence of two loss-of-function alleles in both ClC-K channels (CLCNKA and CLCNKB), as a digenic trait, leads to severe renal salt wasting and sensorineural deafness, which is classified as type IV BS." (PMID 38069401, 2023).
teratoma (1 paper, 2024). A non-seminomatous germ cell tumor characterized by the presence of various tissues which correspond to the different germinal layers (endoderm, mesoderm, and ectoderm). "However, only amplifications of CLCNKA and CLCNKB on 1p36.13 were noted in most (6/9) teratomas in this study." (PMID 38907278, 2024).
kidney disease (6 papers, 2008 to 2024). "In the present case, comprehensive genetic testing using a next-generation sequencer demonstrated no other mutations in over 150 genes, including CLCNKB, associated with major hereditary kidney diseases in the patient’s genomic DNA." (PMID 28819721, 2017). "For example, ion channel (CLCNKA and CLCNKB) and transporter (SLC12P6) alteration, which act in concert to regulate volume and ionic concentration by absorption or secretion of ions into the urine, leads to renal disease." (PMID 35055008, 2022).
tumor (2 papers, 2020 to 2022). "The specific gene expression of renal tumor subtype/nephron segment detected by RQ-PCR showed that the tumor expression of CLCNKB gene was relatively low25." (PMID 35568702, 2022). "The potential tumor-suppressing role of CLCNKB, FBXO27, and FXYD6 in PTC requires further validation." (PMID 33553144, 2020).
CLCNKB also shares sentences with these, for which no sentence is quoted: Hypercalciuria (4 papers); cancer (3); Alkalosis (2); clear cell renal cell carcinoma (2); kidney damage (2); cardiac arrhythmia (1); chronic kidney disease (1); colon cancer (1); essential hypertension (1); focal segmental glomerulosclerosis (1); genetic disorders (1); gout (1); hyperuricemia (1); Hypocalcemia (1); Hyponatremia (1); renal tubular disease (1); SeSAME) syndrome (1).